ALB (albumin)
Diseases named in the same sentence as ALB in open-access papers (continued):
Sharing a sentence is not in itself a finding about the gene and the disease.
Cirrhosis (continued). "A meta-analysis of 16 RCTs also suggested that albumin use was associated with a significant reduction in mortality (odds ratio, 0.46; 95% CI, 0.25 to 0.86) and renal impairment (odds ratio, 0.34; 95% CI, 0.15 to 0.75) in patients with cirrhosis and any infection." (PMID 25042164, 2014). "In summary, cirrhosis, male sex, and obesity are key risk factors for HCC in patients with CHB, while dyslipidemia treated with statins, higher platelet counts, and serum albumin levels are associated with reduced risk." (PMID 41575955, 2026). "On multivariate analysis, albumin and decompensated cirrhosis at presentation were found to be significant independent factors for poor outcomes (OR 0.814 [95% CI 0.670–0.989], p = 0.039; OR 0.146 [95% CI 0.022–0.963], p = 0.046)." (PMID 41601757, 2026). "These patients were predominantly male and had cirrhosis, lower platelet levels (<200,000 103/mL), reduced albumin levels, and elevated alpha-fetoprotein (AFP) levels." (PMID 41379183, 2025). "In conclusion, the present study demonstrated that serum albumin and ammonia levels are associated with the development of OHE in geriatric cirrhosis." (PMID 40928524, 2025). "In this retrospective observational cohort study of patients with cirrhosis and ascites who underwent 2 or more LVPs within 30 days, only 41% received albumin at the time of LVP, despite clinical recommendations." (PMID 41021268, 2025). "For example, a recent retrospective study of patients with cirrhosis and diuretic-resistant ascites receiving outpatient albumin reported reductions in hospital admissions and improvements in biochemical markers, although only a subset underwent LVP." (PMID 41021268, 2025). "The complex interplay among different severity of ascites and cirrhosis, and the dosage and duration of long-term albumin added uncertainty to the true effect of this treatment on patients with cirrhosis and ascites." (PMID 40143117, 2025). "HCC patients showed significantly higher TB, DB, and AFP levels than those cirrhosis and control groups, whereas ALB and Total Protein exhibited significantly reduced levels." (PMID 39753619, 2025). "Patients with advanced schistosomiasis have impaired albumin production and decreased blood albumin levels due to decompensated cirrhosis, which further leads to ascites production." (PMID 40424464, 2025). "The estimated serum immunoglobulin level, based on the difference between serum total protein (7.3 g/dL) and albumin (2.1 g/dL), is relatively high, which is thought to be due to the effects of cirrhosis." (PMID 40704273, 2025). "Serum albumin and ammonia levels were identified as independent risk factors for the development of OHE in geriatric cirrhosis." (PMID 40928524, 2025). "As expected, lower albumin and platelets, and higher AST and ALP, were significantly associated with fibrosis/cirrhosis." (PMID 39717508, 2025). "In this context, this study was conducted to evaluate the efficacy and survival benefit of response-guided therapy with midodrine combined with weekly albumin in diuretic intractable or recurrent ascites in patients with cirrhosis." (PMID 39912014, 2025). "Other ratios, including the LMR, PNR, and neutrophil–lymphocyte–albumin ratio, showed significant differences (p-value < 0.001), indicating more systemic inflammation in cirrhosis." (PMID 40364106, 2025). "This review summarizes the emerging pharmacological approaches for treating ascites in different stages of cirrhosis, encompassing antiplatelet agents, anticoagulants, NSBBs, long-term albumin infusion, and SGLT2i, and highlights the knowledge gaps." (PMID 40143117, 2025). "Diseases such as liver cancer and cirrhosis not only reduce albumin synthesis, but also alter its structure and function, leading to complications associated with impaired physiological functions." (PMID 41187199, 2025).
Cirrhosis (continued). "Reductions in platelet counts and serum albumin were observed only in patients with cirrhosis; Italian cirrhotics had lower albumin values than migrant cirrhotics (4.0, 3.6–4.2 g/dL vs. 4.1, 3.8–4.4 g/dL; p = 0.012)." (PMID 40729522, 2025). "Six patients were categorized Child Pugh A, six patients were categorized Child Pugh B, and one patient was categorized Child Pugh C. Albumin was below standard value in six patients, while the other cirrhosis patients had normal albumin levels." (PMID 39860069, 2025). "Until then, albumin should remain a key but tailored component of cirrhosis management, guided by clinical context and resource availability." (PMID 41140983, 2025). "We aimed to evaluate the efficacy and survival benefits of oral vasoconstrictor and weekly albumin therapy in patients with diuretic intractable and recurrent ascites in cirrhosis." (PMID 39912014, 2025). "Low serum 25(OH)D3 levels, low serum albumin levels, and the presence of esophageal varices were positively associated with CHE in patients with cirrhosis, particularly in those aged <75 years." (PMID 40142666, 2025). "Significant differences were observed in laboratory parameters, with cirrhosis patients showing lower hemoglobin, platelet count, and albumin levels alongside higher liver enzymes and INR values." (PMID 40364106, 2025). "A decline in albumin levels signifies hepatic dysfunction and is frequently detected in patients with advanced fibrosis and cirrhosis." (PMID 40361937, 2025). "In decompensated cirrhosis, serum albumin experiences structural and functional abnormalities, jeopardizing its antioxidant, scavenging, immune-modulating, and endothelium-protective functions." (PMID 40591542, 2025). "In patients with advanced cirrhosis, ALB levels decrease by 60–80%, accompanied by multiple post-translational modifications that alter its structure and functional properties." (PMID 40297155, 2025). "In patient with decompensated cirrhosis, medium to long‐term (12 weeks to 18 months) albumin infusions result in reduced levels of circulating inflammatory cytokines, improve circulatory function and overall survival." (PMID 36800487, 2025). "The blood total bilirubin levels were also higher and platelet and albumin levels were lower in the transplanted patients, indicative of more severe cirrhosis." (PMID 40655475, 2025). "Lastly, albumin is used as an intravenous treatment to extend plasma in hepatorenal syndrome, which can be a vascular-related complication of cirrhosis, making this already approved therapeutic ideal to be repurposed for treatment of other diseases." (PMID 40806286, 2025). "In patients with decompensated cirrhosis, treatment with human serum albumin was shown to reduce the degree of systemic inflammation via the inhibition of the NF-κB pathway." (PMID 40806286, 2025). "Liver ultrasound excluded cirrhosis, while preserved renal function and normal serum albumin made nephrotic syndrome unlikely." (PMID 41267699, 2025). "Several ML studies have also identified serum albumin, ALT, platelet count, and hemoglobin as significant risk factors for decompensated cirrhosis." (PMID 41226084, 2025). "Albumin is a known antioxidant with immunomodulatory properties which are regularly clinically relied upon for the treatment of cirrhosis." (PMID 40806286, 2025). "Given the patient's profound immunocompromised state (Child-Pugh C cirrhosis with albumin 2.3 g/dL) and slow clinical response, CEZ was continued with gradual improvement of inflammatory markers." (PMID 41450394, 2025). "Patients with HCC and cirrhosis showed significantly lower albumin levels (P < 0.0001) compared to the control group with a substantial variation as lower in patients with HCC than the cirrhotic group when compared to control group." (PMID 39753619, 2025). "In patients with hyponatremia and cirrhosis, treatment includes fluid restriction, loop diuretics, potassium supplementation, and albumin administration." (PMID 40922353, 2025).
Cirrhosis (continued). "Patients with cirrhosis often have low albumin levels compared to the general population, reduced blood pressures at baseline, an impaired immune response, excessive oxidative stress, and are prone to fluid accumulation in the extravascular space." (PMID 40386509, 2025). "Regarding treatment focus and strategy, cirrhosis management emphasizes supporting liver function and managing complications, such as albumin supplementation and ascites control." (PMID 41312479, 2025). "Further clinical investigation would be needed to connect the pathophysiological advantages of albumin use in patients with cirrhosis and septic shock to clinically impactful outcomes." (PMID 40386509, 2025). "Across the selected trials, albumin infusion consistently demonstrated benefits in reducing complications of decompensated cirrhosis." (PMID 41140983, 2025). "In a study of 117 patients with cirrhosis in Germany, high MELD scores and low serum albumin levels showed an independent association with CHE." (PMID 40142666, 2025). "As serum albumin and ammonia levels were independent factors associated with OHE development in geriatric cirrhosis, the impact of the sHE scores derived from these variables was also examined using multivariable analysis." (PMID 40928524, 2025). "For instance, albumin, a natural colloid, is valuable in specific cases, such as in cirrhosis, post bypass surgery, and severe septic shock." (PMID 40766965, 2025). "This systematic review evaluated the role of human albumin infusion in patients with decompensated cirrhosis, refractory ascites, acute-on-chronic liver failure (ACLF), and hepatorenal syndrome type 1 (HRS-1)." (PMID 41140983, 2025). "The recorded gradient of the ALBI index reinforces its utility in stratifying liver dysfunction, with cirrhosis cohorts exhibiting significantly impaired albumin production and bilirubin clearance." (PMID 40647574, 2025). "The American Association for the Study of Liver Diseases (AASLD) recommends the administration of albumin in conjunction with LVP to prevent further complications of cirrhosis." (PMID 41021268, 2025). "We have previously developed a simple HE (sHE) score using serum albumin and ammonia levels to identify the risk of developing CHE and OHE in patients with cirrhosis." (PMID 40928524, 2025). "Patients with the following features were excluded: ALT or AST > 250 (n = 662), missing BMI, AST, ALT, platelet count, or albumin levels (n = 2,839), missing race/ethnicity (n = 122), and codes for cirrhosis or HCC at the time of study entry (n = 236)." (PMID 41144490, 2025). "Consideration of these factors as correlates of short‐term mortality, alongside traditional laboratory markers like albumin and bilirubin, is warranted in evaluating cirrhosis patients in the ED." (PMID 39776102, 2025). "Summary of randomized controlled trials assessing albumin infusion in advanced cirrhosis and its complications." (PMID 41140983, 2025). "Albumin infusion reduces inflammatory cytokines, endotoxins, and oxidative stress, and consequently improves HE in patients with cirrhosis." (PMID 40928524, 2025). "Conditions like liver cancer and cirrhosis not only reduce albumin synthesis but also alter its structure and function." (PMID 39831739, 2025). "The Child–Pugh score remains a cornerstone tool for assessing cirrhosis severity, integrating both clinical (ascites, encephalopathy) and biochemical parameters (bilirubin, albumin, INR)." (PMID 41300878, 2025). "Albumin was significantly associated with the Child–Pugh score (p < 0.01) and showed a notable interaction between HCC stage/cirrhosis and the Child–Pugh score (p < 0.01)." (PMID 40183893, 2025). "We confirmed that the commonly tested clinical and demographic markers in cirrhosis patients, including ALT, total bilirubin, albumin, platelet count, and age, are strong risk factors for decompensation." (PMID 41226084, 2025).
Cirrhosis (continued). "Albumin group had higher survival (86% vs 57%, p=0.016), fewer cirrhosis-related complications, and fewer hospital days; admissions were similar." (PMID 41140983, 2025). "Albumin administration has reduced mortality in patients with cirrhosis with other disease states, such as spontaneous bacterial peritonitis and hepatorenal syndrome." (PMID 40386509, 2025). "According to Grønkjaer, patients with cirrhosis and AP had more cirrhosis-related issues and lower albumin levels and higher CRP." (PMID 40308406, 2025). "After univariate and multivariate logistic regression analysis, the cirrhosis, PVP hypo-enhancement, elevated AFP level (> 40 ng/mL), and lowered albumin level (< 29 g/L) were decided as independent risk factors of MTM-HCC in the training set (all p < 0.05)." (PMID 41105281, 2025). "Despite conventional treatments for decompensated cirrhosis, such as hepatoprotective therapy, sodium-restricted diuretics, ascites drainage, and human serum albumin infusions, the patient’s hepato-renal function and ascites showed no significant improvement." (PMID 41458624, 2025). "Real‐world evidence supporting the beneficial effects of long‐term albumin use in decompensated cirrhosis." (PMID 39301299, 2024). "In hepatic encephalopathy, albumin infusion is thought to improve cognitive function by reducing ammonia concentration in blood and thereby tackle cirrhosis-induced hepatocyte malfunction in ammonia clearance." (PMID 38551716, 2024). "Older age, male gender, low serum albumin levels, and high LSM were found to be risk factors for HCC after SVR in hepatitis C patients with advanced fibrosis and cirrhosis." (PMID 38664813, 2024). "Infused albumin can also exhibit protective effects by binding to the cirrhosis-induced proinflammatory cytokines TNFα and IL6." (PMID 38551716, 2024). "A clinical study also demonstrated the role of albumin in cardiac contractility in patients with cirrhosis." (PMID 38892040, 2024). "Terlipressin and albumin are more effective in improving renal function in patients with cirrhosis and hepatorenal syndrome." (PMID 39286706, 2024). "The patients who underwent LDLT were suggested to be approaching cirrhosis because of decreased serum albumin and unchanged serum total protein over time, thereby the gradual decrease in the A/G ratio." (PMID 38341604, 2024). "Only when the body has chronic liver parenchymal injury, such as chronic hepatitis and cirrhosis, the serum TP and ALB are reduced due to the obvious impairment of hepatocyte protein synthesis function." (PMID 39469332, 2024). "In cirrhosis, the albumin/globulin ratio (A/G ratio) is decreased because of decreased albumin synthesis in the liver and increased immunoglobulin associated with chronic inflammation." (PMID 38341604, 2024). "A retrospective study was conducted to evaluate the influence of the timing of albumin administration on the length of stay and total hospital cost for patients with cirrhosis and spontaneous bacterial peritonitis who require fluid resuscitation." (PMID 38899040, 2024). "Portosystemic shunts found in cirrhosis patients can worsen cardiac function due to an extremely rapid shift of blood from the splanchnic circulation to the heart after albumin infusion." (PMID 38551716, 2024). "The clinical potential of long‐term albumin infusions supported by recent clinical trials has expanded its indications and holds promise to transform the management and secondary prevention of cirrhosis‐related complications." (PMID 39301299, 2024). "In the decompensated stage of cirrhosis, low albumin and high bilirubin levels indicate severe liver dysfunction and poor prognosis." (PMID 38191888, 2024). "Prostaglandin (PG) E2 was absent from the albumin of patients with acute uncompensated cirrhosis, suggesting that it is mainly present in this group of patients in a form separated from albumin." (PMID 39273468, 2024).
Cirrhosis (continued). "The patient’s overall recovery was slow due to decreased albumin (ALB) and increased procalcitonin (PCT) caused by the patient’s cirrhosis." (PMID 39654192, 2024). "Accurate patient selection is a key factor, and our study identified older age, concomitant cirrhosis, low serum albumin, higher serum creatinine, and MELD scores exceeding 30 as predictive factors for non-response." (PMID 38399598, 2024). "By contrast, patients with a cholestatic pattern doubled the risk of cirrhosis compared to the mixed and hepatocellular pattern, and, probably, this fact explains the lower percentage of MASH and albumin levels in the presence of cholestasis." (PMID 38619600, 2024). "The ANSWER clinical trial which investigated the long-term administration of human albumin in patients with decompensated cirrhosis showed improvements in hemodynamic stability, renal function, and overall survival." (PMID 38551716, 2024). "Clinicians should aggressively manage AKI in hospitalized patients with cirrhosis especially in patients with MASLD-cirrhosis, higher Cr at admission, and low Albumin at admission since they are at risk of persistent AKI upon discharge." (PMID 39518516, 2024). "The use of albumin in critically ill patients with cirrhosis and AKI should be approached with greater consideration of its risks and benefits." (PMID 39434907, 2024). "The ANSWER randomised-controlled trial has shown that long-term albumin treatment (LTA) is an effective approach for the management of patients with cirrhosis and ascites." (PMID 39640220, 2024). "Albumin plays an important role in the management of decompensated cirrhosis in Australia, reflecting global trends in hepatology." (PMID 39301299, 2024). "The data suggests that future research should focus on conducting large-scale, multicenter prospective trials, to evaluate the optimal dosage, duration, clinical efficacy, and cost-effectiveness of albumin in patients with cirrhosis and SBP." (PMID 38899040, 2024). "Patients with advanced cirrhosis experience reduced albumin production and poor hepatocellular function, resulting in a 60–80% reduction." (PMID 38561807, 2024). "Specifically, patients with compensated cirrhosis exhibit stronger correlations between albumin, prothrombin time, and bilirubin (representing different aspects of liver function)." (PMID 38961593, 2024). "Albumin and ALT were exceptions to this pattern, as for these LBTs, individuals in the ‘high’ PGS group had a significantly higher risk of cirrhosis morbidity (p < .01)." (PMID 39425533, 2024). "They observed that the decrease in effective serum albumin was greater than the decrease in total serum albumin in cirrhosis patients with SBP and renal failure." (PMID 38551716, 2024). "The age of cirrhotic patients, serum albumin and prothrombin time are frequently reported as predictors of prognosis in patients with compensated and decompensated cirrhosis." (PMID 39597844, 2024). "The same study also identified CCNB1 and CCNB2 as DEGs and pathologically related to cirrhosis and serum albumin." (PMID 39452074, 2024). "PLT was lowest in cirrhosis (170,718.67 ± 124,250.94 cells/mm3), and serum albumin levels were significantly lower in cirrhosis (2.69 ± 0.67 g/dl)." (PMID 39650982, 2024). "So, it is possible that cirrhosis-induced alterations in the native albumin incapacitates the binding of albumin to toxins and pro-inflammatory cytokines, thereby hampering its usual anti-inflammatory functions." (PMID 38551716, 2024). "The relative concentration of unaltered native albumin was significantly lower in patients with cirrhosis." (PMID 38551716, 2024). "Other significant factors include more advanced age, lower platelets, lower albumin, presence of cirrhosis, and evidence of portal hypertension." (PMID 38273255, 2024). "Diabetes is prevalent in patients with cirrhosis and hyperglycaemia-induced physiological stress adds to this damage to albumin." (PMID 38551716, 2024).